CD4 (CD4 molecule)
Diseases named in the same sentence as CD4 in open-access papers (continued):
Sharing a sentence is not in itself a finding about the gene and the disease.
tumor (continued). "OT-II Foxp3EGFP mice are essentially devoid of nTreg, having transgenic CD4 T cells that recognize a class II-restricted epitope derived from ovalbumin; Foxp3 expression could not be detected in TIL or SPL in these mice when implanted with ovalbumin-transfected B16 tumor (B16-OVA)." (PMID 22112546, 2011). "Notably, CD4+ and CD8+ cell subsets could be depleted before immunization or tumour challenge in BALB/c mice, without any significant effect on inhibition of tumour growth, while the combined depletion in the induction phase abrogated tumour protection." (PMID 20657846, 2010). "In order to fully utilize the complete repertoire of cytokines secreted by activated lymphocytes in a simple yet effective manner, we hypothesize that nonspecifically-activated CD4+ lymphocytes (aCD4) can pre-sensitize tumor cells to enhance the apoptotic effect of gamma radiation." (PMID 20178622, 2010). "Since our group and others have shown that Her2 can down-modulate MHC class I expression, tumor vaccine strategies such as pDNA administration that are not solely dependent on CTLs but induce an integrated immune response involving also antibodies and CD4+ T-cells should be advantageous." (PMID 20529245, 2010). "We have demonstrated that pre-sensitization of tumor cells with non-specifically activated CD4+ T cells greatly enhanced the apoptotic effect of γ-irradiation, and that soluble factors secreted from the activated CD4+ T cells were primarily responsible for the observed effect." (PMID 20178622, 2010). "However, it is not clear whether the infiltration of CD4+ T-lymphocytes within the tumour is a sign of an active immune response or whether it is a more passive consequence of cytokine excretion from the tumour that attracts T lymphocytes." (PMID 14612901, 2003). "Immunohistochemically, tumor cells are usually positive for CD3, CD8, CD56, TIA-1, granzyme B, and perforin, and negative for CD4 and CD5, consistent with the findings in our patient." (PMID 41328359, 2026). "In tumor dynamics, new antigens are generated that encounter immune cells, such as antigen-presenting cells (APCs), that activate cytotoxic CD8+ T and CD4+ T lymphocytes, although this reaction is not efficient in suppressing tumor cells." (PMID 41596472, 2026). "By contrast, PD‐1/CTLA‐4 dual blockade neither restored CD4+ T cell infiltration nor enhanced IFN‐γ and Granzyme B production, consistent with its limited anti‐tumour activity." (PMID 41492119, 2026). "In some preclinical and clinical studies, the anti-tumor function of CD4 + T cells in the absence of CD8 + T cells has been reported, indicating a more direct role of CD4 + T cells in anti-tumor immunity." (PMID 40587482, 2025). "Among the 186 clones that were not preferentially enriched in either the tumor or NILT, 80 are dominated by CD4+ T cells and 27 by CD8+ T cells." (PMID 40777278, 2025). "Subsequent flow cytometry analysis of tumor-infiltrating lymphocytes revealed a notable increase in the proportion of CD8+ T cells in the B7-H3 overexpression group, while CD4+ T cells displayed no significant alterations." (PMID 39990209, 2025). "The results demonstrated a notable increase in NCL expression levels in isolated CD8+ T cells from tumor tissue as opposed to normal lung tissue, whereas the expression of NCL in CD4+ T cells and Treg cells showed no significant change." (PMID 40346484, 2025). "Moreover, chronically stressed tumour‐bearing mice displayed the largest tumour volumes, suggesting that the CD4+/CD8+ ratio may not always be an accurate biomarker or predictor of patient outcome when high stress (cortisol) levels are factored into the equation." (PMID 40172096, 2025). "IHC staining for CD4 and CD8 in tumor tissues revealed almost no positive staining in the saline and PD-1 groups." (PMID 40104638, 2025).
tumor (continued). "In non-TDLNs, effector/effector memory T cells and CD4+ T cells trended downward, whereas effector/effector memory CD8+ T cells increased, suggesting their trafficking to the tumor site for cytolytic action." (PMID 40573908, 2025). "Moreover, co-incubation of exosomal GAS5 with CD4+ T cells inhibited their differentiation into an IFN-γ-producing Th1 phenotype, skewing it towards an IL-4-producing Th2 phenotype, in part by downregulating the transcription factor T-bet, which may promote tumor cell survival." (PMID 40429961, 2025). "Strikingly, we found that ATP at concentrations found in tumor and infectious environments inhibits anti-CD3/CD28–stimulated CD4+ T cells from noninfected control mice." (PMID 40590226, 2025). "The tumor suppressive effect of aCD40 was abolished in the absence of CD8 + or CD8 + and CD4 + T cells, but was unaffected in hosts that were depleted of only CD4 + T cells." (PMID 40585246, 2025). "The frequency of surviving tumor cells was increased in mice injected with the anti-MHCII antibody, which was not significant compared to mice given saline-treated CD4+ T cells." (PMID 39885128, 2025). "By comparing the proportional differences between recurrent and non-recurrent tumor cells, we found that CXCL13+ CD4+ and CD8+ T cell subsets were enriched in non-recurrent tumors." (PMID 40464813, 2025). "In contrast to tumor tissues, CD8+ T cells in normal tissues demonstrated less interactions alongside Treg cells, while Treg cells and CD4+ T cells virtually lacked interactions, albeit exhibiting significantly enhanced effects on NK cells." (PMID 40723292, 2025). "In vivo depletion of CD4+ and CD8+ T cells simultaneously or CD8+ T cells alone did not influence tumor growth but completely reversed the tumor growth inhibition induced by anti-PD1 therapy." (PMID 40038236, 2025). "CD3-positive, CD4-positive, and CD8-positive TIL subpopulations in the primary and in the recurrent tumor were prevalent in peritumoral areas rather than in the tumor core." (PMID 40165973, 2025). "Both B and Tfh cells were critical for tumor control, as implanting tumors in mice lacking B cells (uMT mice), functional MHC-II (CDIIA knockout mice), and Tfh cells (Bcl6 knockout in the CD4 lineage) resulted in increased tumor growth." (PMID 40356924, 2025). "This indicated that the primary effector cells of the anti-tumor immune response were proliferative and activated CD20+ B cells, CD21+ DCs, and CD4+ Th cells, rather than CD8+ cytotoxic T cells within tumor-region M-TLSs." (PMID 40918107, 2025). "Without CD4+ T cell help, CD8+ T cells tend to become exhausted, which limits their anti-tumor effectiveness." (PMID 40177538, 2025). "Cancer vaccines represent a promising therapeutic approach in PC, designed to elicit robust tumor-specific CD4+ and CTL responses via recognition of tumor cells (non-antigen-specific) or TAAs (antigen-specific)." (PMID 40051495, 2025). "The interpretation of this data must be treated with caution since the roles of CD4+ and CD8+ T cells in anti‐tumour immunity are not well defined." (PMID 40172096, 2025). "Here, we characterized the antitumor activity of anti-TGF-β CAR T cells and found that their CD4+ but not CD8+ compartment induced the death of cancer cells in vitro and robustly suppressed the growth of various tumor models." (PMID 40107245, 2025). "In contrast to MISTRG-6 mice, NSG-Quad mice did not improve human NK cell development in the blood, and the frequency of human CD4+ and CD8+ T cells was reduced in the blood and spleen but not in the tumor of NSG-Quad mice." (PMID 40503011, 2025). "No clear evidence of a decrease in circulating tumour DNA or changes in peripheral immune cells, including CD8+ and CD4+ T cells, DCs, and myeloid-derived suppressor cells, was observed." (PMID 41294666, 2025).
tumor (continued). "Nemvaleukin increased tumor-infiltrating CD4+ and CD8+ T cells, promoted the expansion of non-regulatory T-cell populations, and significantly slowed tumor growth compared to controls and recombinant human IL-2 (rhIL-2) treatment." (PMID 40636453, 2025). "used an in vitro transwell migration assay to show that conventional dendritic cells (cDCs) and B cells, but not CD4+ or CD8+ T cells, were attracted by tumor microenvironment (TME)-conditioned media from different anatomical sites." (PMID 40453074, 2025). "Directed with a CD4-specific CAR for T cell malignancies, they significantly improved xenograft tumour control compared to non-transduced control cells, which was then further enhanced by idelalisib pretreatment." (PMID 41463563, 2025). "There was minimal talaporfin incorporation in tumor-infiltrating CD4+ or CD8+ T cells in vivo, compared to its higher presence in nonimmune CD45- cells, which were predominantly tumor cells." (PMID 39842944, 2025). "Neither pulse protocol significantly affected the proximity of CD4+ and CD8+ T cells to CD31+ endothelial cells in the tumor vessels, nor did they alter the area of the tumor vessels at any of the examined time points." (PMID 39967849, 2025). "Our results indicated a significant increase in CD4 + and CD8 + T cells in the tumour micro-environment, rather than peripherally following treatment with anti-PD-1 and anti-TIGIT." (PMID 39939955, 2025). "We further observed TIM3-positive T cells in tumor-bearing TCL1 AT but not WT mice, with the highest frequencies detected in CD8 TEF and CD4 TREG cells." (PMID 40775219, 2025). "Preliminary experiments indicated an increase in the CD8/CD4 ratio and a two-fold increase in the expansion capacity of CAR-T cells without tumor stimulation when B2M and CIITA were knocked down." (PMID 39856752, 2025). "In contrast, an increase in CD4+ TGF-β1+ T cells and CD8+ Temra cells was significantly noted in ICB-NRs, which we named tumor-non-responsive T cells (TNRTs)." (PMID 40054456, 2025). "At initial diagnosis, the patient’s IFN-γ and CD4+/CD8+ ratio were within normal ranges, suggesting that although the immune system was not completely dysfunctional, the tumor had formed metastatic lesions through immune escape mechanisms." (PMID 40959071, 2025). "Quantitation using TCR network analysis further corroborated that cytotoxic CD4+ (GZMB+ and GZMK+) T cells were significantly overrepresented in clusters of tumor-blood matched TCRs over nonmatched TCRs in blood and tumor." (PMID 40299576, 2025). "For the first tumor, neither KLRG1– nor KLRG1+ CD4+ T cells from PBMCs increased tumor cell death when coincubated without treatment." (PMID 40299576, 2025). "Whereas tumor-responsive CD8+ T cells in the TIL products failed to produce cytokines, CD4+ T cells not only displayed increased PD1 expression ex vivo but also produced TNF in response to autologous tumor digest." (PMID 40897471, 2025). "On day 3, image analysis of tumor edges revealed an initial decrease in the number of CD4+ and CD8+ T cells compared with that in control tumor tissues, regardless of the electric pulse protocol used." (PMID 39967849, 2025). "Among PRs, there was an increased correlation of CD4+ and CD8+ T cells outside and within the tumor compared to non-PRs." (PMID 41542091, 2025). "LSP1 exhibited a negative correlation with tumor purity but demonstrated a positive correlation with the infiltration levels of various immune cells, including B cells, CD8+ T cells, CD4+ T cells, neutrophils, and dendritic cells." (PMID 40038352, 2025). "Within tumor, blood-matched TCR phenotypes were predominantly not proliferating, but were instead consistently cytotoxic (GZMB+ and GZMK+ for CD4+, also GZMK+ and MAIT for CD8+), and also included noncytotoxic CXCL13+ CD4+ and Tregs as observed above." (PMID 40299576, 2025).
tumor (continued). "Similarly, the negative correlation with CD4+ memory T cells, which play a crucial role in anti-tumor immunity and can suppress tumor growth by enhancing anti-tumor immune responses, indicates that PRR13 might inhibit their function within the tumor microenvironment." (PMID 40099041, 2025). "The IMC findings were confirmed with quantitative immunofluorescence (QIF) staining and analysis, which also showed no overall differences between CD4+ and CD8+ T cells or B cell infiltration into the tumor environment (data not shown)." (PMID 40459946, 2025). "tumor biopsies profiled showed increased amounts of CD8+ T cells, CD4+ T cells and NK cells after intravenous TILT-123, but not after intratumoral TILT-123." (PMID 39870491, 2025). "In this regard, T cells were consistently less than 5% of total cells in the NB TME, consisting of both CD4+ and CD8+ T cells, more frequently detectable in septa rather than in tumor cell nests, CD8+ being predominant over CD4+T cells." (PMID 40092980, 2025). "The findings revealed a significant decrease in the number of NCL+CD8+ T cells in tumor tissue compared to normal lung tissue, while the quantities of NCL+CD4+ T cells and NCL+Treg cells showed no significant variation." (PMID 40346484, 2025). "We observed that the absence of CD4+T and CD8+ T cells promotes tumor growth compared to vehicle-treated group." (PMID 40475776, 2025). "In comparison, TIGIT mAb-treated mice exhibit higher frequencies of tumour-infiltrating CD8+ T cells expressing IL2/TNF-α/IFN-γ and CD4+ T cells expressing IL2, without altering the ratio of memory CD4+ T cells." (PMID 40994140, 2025). "Evidence for the prognostic significance of shared clones is supported by the observation that responders to anti-CD4 monoclonal therapy exhibit a greater expansion of shared CD8+ clones, detected in both blood and tumour compared to non-responders." (PMID 40801654, 2025). "The investigators found that HCC had a lower baseline CD4+ CTLA4+ lymphocytes and Tregs, compared to non-HCC neoplasms." (PMID 41041128, 2025). "In the present study, it is found that oAd-SA slightly upregulated the percentage of T lymphocytes including CD3+, CD4+ and CD8+ T cells within tumor tissue as compared to oAd-ON, but no statistical significance was achieved between these two groups." (PMID 40070841, 2025). "Given the crucial and diverse roles of tumor-infiltrating T cell subtypes in immunotherapy, we classified T cells into 10 subsets based on canonical makers, including seven CD8+, two CD4+, and one double-negative (CD4−CD8−) T cell subtypes." (PMID 40312419, 2025). "In IKE-treated TIPE2−/− LLC tumor-bearing mice, increasing the accumulation of immunostimulatory MDSCs can promote effector CD4+ and CD8+ T cells, not immunosuppressive Tregs, to infiltrate into the tumor tissues." (PMID 39851538, 2025). "In summary, tumor-intrinsic ZBP1-dependent necroptosis is necessary for recruitment of APCs and effector CD4+ and CD8 + T cells in distant, non-irradiated tumors, and is essential for abscopal responses to RT + ICI + PARP7i." (PMID 41282221, 2025). "In the bone marrow of MC38 tumor-bearing mice, CD310+ was expressed mostly on CD11b+myeloid cells but was absent from T CD8+and T CD4+ lymphocytes." (PMID 41459512, 2025). "Data analysis revealed that, in the T cell populations, CD3, CD4, and CD8 T cells did not change after treatment in the tumor and spleen." (PMID 40643531, 2025). "Particularly, CD4+ but not CD8+ T28zT2 T cells expanded robustly and inhibited tumor growth in vivo." (PMID 40107245, 2025). "In PB samples of patients with FIGO stage IV, percentages of cDC2, CD57+ CD16- NK cells, and CD4+ TTM were increased, whereby these differences were not seen in ascites or tumor samples." (PMID 41221283, 2025). "In vivo, the specific contributions of CD4+ and CD8+ T cells to the formation of anti-tumor memory T cells were not fully delineated." (PMID 41294838, 2025).
tumor (continued). "Although tumor tissues treated with ribociclib or trametinib as monotherapies tended to show more CD3- and CD4-positive cells, combination therapy did not change CD3/CD4/CD8 expressions compared with those of tumors that received vehicle." (PMID 41428766, 2025). "Interestingly, only E0771 tumor-bearing mice fully resisted tumor recurrence, which may be attributed to varying amounts of natural immune cells, indicating the importance of further evaluation of the myeloid-derived suppressor cells (MDSCs) and CD8+ and CD4+ cells role in the anti-tumor response." (PMID 38672570, 2024). "Subsequently, we compared the expression of exhaustion related molecules in CD4+T cells and found that CD4+T cells in obese tumor samples had higher expression of TIGIT and CTLA4 molecules compared with non-obese tumor samples." (PMID 38311726, 2024). "The densities of tumor-infiltrating lymphocytes (TIL) subsets (TIBs, CD4+ T cells, CD8+CD103+ TRMs, and CD8+CD103- non-TRMs) were quantified and correlated with clinical parameters and overall survival (OS) including the Graded Prognostic Assessment (GPA)." (PMID 39594720, 2024). "In contrast, CD3+CD4/CD8-double negative (CD4−/CD8−DN) T cells, which normally comprise a rare subset of peripheral T cells, forms the largest fraction of all non-tumor cells in LaPN at almost 16%, while it is missing in GoPN." (PMID 39548496, 2024). "Murine models demonstrated that anti PD-1 therapy exerted antitumour effect on MHC-I−MHC-II+ tumours in a cytotoxic CD4+ T cell-dependent manner, while the same effect on MHC-I−MHC-II− tumours was not reached." (PMID 38541208, 2024). "Previous studies have suggested that CD4+ and CD8+ T cell infiltration into malignant tumors not only represents the ongoing anti-tumor response by the host but also correlates with the prognosis of patients with cancer 13,14." (PMID 38356712, 2024). "Although we did not observe any correlations of IL13Ra2 expression with CD4/8 T-cell infiltration or HLA-1 expression, we noticed the HLA-1 expression was not suppressed in the majority of BSG tumor samples." (PMID 38201655, 2024). "Responsive tumours exhibited increased CD4+ T cells, Th1, CD8+ T cells, and effector memory T cells in tumor islets, whereas nonresponder patients' tumour stroma displayed an increased gene signature of M2-like macrophages." (PMID 38833685, 2024). "In summary, we show that including tumor-specific, but not tumor-unrelated, MHC class II-restricted CD4+ T cell antigens in a cancer vaccine resulted in increased control of tumor growth." (PMID 39040850, 2024). "We identified that tumor epithelial expression of NLRC4, rather than stromal, is critical to mediate immune protection through DC and CD4+ and CD8+ T cell immune infiltration into the tumor microenvironment." (PMID 38652550, 2024). "The number of other immune cells such as helper T cells (CD3+ CD4+) and cytotoxic T cells (CD3+ CD8+) was not influenced significantly in the tumor tissues." (PMID 38483163, 2024). "In the spleen tumor microenvironment, although there were some changes in the population of CD4+ T-cells, CD8+ T-cells, effector memory T cells (TEM s) in CD4+ T-cells and CD8+ T-cells, these alterations did not demonstrate statistical significance." (PMID 38911391, 2024). "The absence of YTHDF2 in Treg cells of the tumor microenvironment leads to an increase in CD8+ T cell infiltration and the expansion of the antitumor CD4+ TH1 subset." (PMID 39372415, 2024). "Two doses of two different anti-metabolite chemotherapies increased tumor infiltrating CD4+, and CD8+ TPEX expressing LAG-3 in multiple mouse models, which was not restricted to tumor antigen specific CD8+ T cells." (PMID 39343508, 2024). "Although AlCVCT26@D‐Gel failed to promote tumor infiltration of CD3+ T cells, it led to a similar reduction in Foxp+CD4+ regulatory T cell (Tregs) within CD4+ T cell population as ZCVCT26@D‐Gel." (PMID 38279587, 2024).